REN (renin)
Diseases named in the same sentence as REN in open-access papers (continued):
Sharing a sentence is not in itself a finding about the gene and the disease.
Hypokalemia (continued). "Both presented with hypokalemia, elevated plasma aldosterone, and undetectable renin." (PMID 39803142, 2024). "In certain instances, such as in the setting of spontaneous hypokalemia, suppressed renin activity (PRA) plus plasma aldosterone concentration (PAC) of > 15 ng/dL, one may not proceed with confirmatory tests." (PMID 38978003, 2024). "Therefore, when patients showed refractory hypokalemia, in addition to family history, blood and urine electrolytes, renin-angiotensin system, and other evaluations, genetic testing is necessary for the diagnosis to avoid missed diagnosis and misdiagnosis." (PMID 37131142, 2023). "In case of persistent hypokalemia, potassium-sparing diuretics, renin-angiotensin system blockers, or NSAIDs may be useful." (PMID 37657006, 2023). "According to the ES guidelines and to the European Society of Hypertension (ESH) consensus, confirmatory testing could be skipped in patients with spontaneous hypokalemia, undetectable renin, and PAC > 20 ng/dL." (PMID 37223051, 2023). "The patient had hypokalemia and a high aldosterone/renin ratio." (PMID 36461073, 2022). "Hypokalemia in the setting of SARS-CoV2 infection may result from overactivation of the renin–angiotensin–aldosterone system (RAAS), low intake, and gastrointestinal or kidney loss." (PMID 36042344, 2022). "A review reported that mortality risk progressively increased with dyskalemia and was differentially greater in patients with HF, taking diuretics, and taking renin-angiotensin-aldosterone system inhibitors related to hypokalemia and hyperkalemia, respectively." (PMID 35837353, 2022). "Patients with this type of deficiency develop female genitalia at birth (46, XX, or XY), show an absence of secondary sexual characteristic development at puberty, and exhibit amenorrhea, hypertension, hypokalemia, and suppression of the renin–angiotensin–aldosterone system." (PMID 34290232, 2021). "Blood tests showed hypokalemia (2.0 mmol/L), hypomagnesemia (0.55 mmol/L), hypocalciuria (2.0 mmol/24 h), and renin–angiotensin–aldosterone system (RAAS) activation (renin 49.6 mIU/L, aldosterone 740 pmol/L), metabolic alkalosis, normal renal function, and no proteinuria." (PMID 32926342, 2021). "Hypokalemia is mainly attributed to the activation of the renin/angiotensin/aldosterone system." (PMID 34503561, 2021). "Hypokalemia might have occurred due to administration of diuretics, alkalosis, derangements in the renin angiotensin aldosterone system, gastroenteritis or other pathologies." (PMID 32838735, 2020). "In addition to hypokalemia, metabolic alkalosis, and increased renin activity, the patient in our case also presented with hypomagnesemia and hypocalciuria, which are two indispensable criteria for diagnosing GS." (PMID 29378538, 2018). "The hypokalaemia was presumed second to a perfect storm of HG with subsequent nutritional deficiencies causing electrolyte wasting, extracellular fluid (ECF) volume reduction, and activation of the renin-angiotensin-aldosterone axis (RAAS)." (PMID 30151287, 2018). "Regarding phenotype, and despite the genetic heterogeneity among described type III BS cohorts, the finding of hypokalemia, metabolic alkalosis and increased levels of circulating renin and aldosterone was almost universal in all published series including our cohort." (PMID 28288174, 2017). "Excess aldosterone, inappropriately high for the salt intake status, causes hypertension, cardiovascular and renal damage, sodium retention, suppression of plasma renin, and increased potassium excretion that (if prolonged and severe) may lead to hypokalemia." (PMID 28018978, 2016). "The normal plasma renin activity, normal serum aldosterone, and low urine potassium suggest that this patient's hypokalemia was not caused by renal potassium wasting." (PMID 18625064, 2008).
Hypokalemia (continued). "However, recent studies demonstrate that COX-2 in the macula densa modulates renin secretion, and there is one case report which describes successful treatment of refractory hypokalemia with a COX-2 inhibitor (rofecoxib)." (PMID 16723030, 2006). "The combination of spontaneous hypokalemia and metabolic alkalosis in the context of resistant hypertension is strongly suggestive of primary hyperaldosteronism, but this trio is also seen in Liddle’s syndrome, although in that diagnosis, both renin and aldosterone are suppressed." (PMID 41356982, 2025). "However, for some groups of patients, who present with spontaneous hypokalaemia, plasma renin activity below detection levels, and PAC > 0.55 nM/dm3, a confirmatory test may not be necessary." (PMID 38255973, 2024). "However, it has been contended that AVS is not necessary for young patients under 35 years of age with a confirmed PA (a high ARR, undetectable renin, and spontaneous hypokalaemia) and radiological features of unilateral APA with a contralateral normal adrenal." (PMID 38255973, 2024). "Hypokalemia in SARS-CoV-2 infection may occur due to hyperactivation of the renin-angiotensin-aldosterone system, GI loss, lack of appetite because of concurrent illness, and damage of the tubules due to ischemia or nephrotoxic agents." (PMID 36860825, 2023). "As a term of comparison, the diagnostic performance of the current criteria of ES guidelines, according to which confirmatory testing could be skipped in patients with spontaneous hypokalemia, undetectable renin, and PAC > 20 ng/dL, was also evaluated in our cohort." (PMID 37223051, 2023). "However, other studies demonstrated that increasing of circulating renin, angiotensin II, and aldosterone by hypokalemia-independent volume depletion might be a more important factor of renal impairment and fibrosis." (PMID 30413979, 2019). "PLS-DA and PCA confirmed that renin in OP, renin response to PST, and hypokalemia were the most relevant parameters for distinguishing PA from low-renin HTN." (PMID 41251951, 2025). "SARS-CoV-2 disrupts the renin–angiotensin–aldosterone system via ACE2 downregulation, favoring kaliuresis and hypokalemia; diuretic exposure, diarrhea, and corticosteroid use further amplify these impairments in hospitalized cohorts." (PMID 41010381, 2025). "This leads to an imbalance in the renin-angiotensin-aldosterone system (RAAS), which leads to hypertension and hypokalaemia." (PMID 41439054, 2025). "However, the suppressed renin and aldosterone activity due to the fluid overloading status in nephrotic syndrome might hamper the standard management, and therefore the hypokalemia might be corrected by spironolactone even with the proximal tubular dysfunction." (PMID 37061666, 2023). "The CKD in BS seems to have several mechanisms: chronic stimulation of the renin–angiotensin system, periodic dehydration, prematurity, nephrocalcinosis, long-term NSAID drug treatment, and chronic hypokalemia." (PMID 35722471, 2022). "Clinical and biochemical remissions were assessed on postoperative BP measurement, antihypertensive drug dosage, aldosterone-to-renin ratio (ARR), and normalization of hypokalemia." (PMID 36412687, 2022). "Among 32 patients treated medically, 12 had persistent renin suppression (PRA <1ng/ml/h), whereas four had hypokalemia at their 1-year clinic visit." (PMID 35846272, 2022). "Disrupted renin-angiotensin-aldosterone system (RAAS) activity and hypokalemia are fundamental aspects of PA; furthermore, aldosterone-induced hypokalemia has been reported to impair glucose tolerance by impeding insulin secretion." (PMID 33967948, 2021). "Biochemically, the characteristic findings are hypokalemia, metabolic alkalosis, suppressed PRA (plasma renin activity) and low serum aldosterone levels." (PMID 29534496, 2018).
Hypokalemia (continued). "Laboratory tests demonstrated severe hypokalemia (2.7 mmol/L), metabolic alkalosis, hypomagnesemia, renal potassium wasting, hypocalciuria, elevated renin and aldosterone, and a negative diuretic screen, consistent with GS." (PMID 41815885, 2026). "While it usually presents with elevated renin and aldosterone levels and hypokalemia, normal laboratory findings do not rule out the diagnosis." (PMID 41357681, 2026). "Preoperative hypokalemia was cured in all, aldosterone levels were significantly reduced, and renin became unsuppressed, and, because of these changes, ARR normalized (P-value < 0.001)." (PMID 39551865, 2025). "Persistent hypokalemia rather than discrete attacks; supporting clues from blood pressure, renin–aldosterone profile, diuretic history, and chronic metabolic alkalosis." (PMID 41523487, 2025). "In addition, the plasma aldosterone concentration (PAC) was lower, plasma renin activity (PRA) higher, and hypokalemia (P < 0.001) less frequent than in sporadic cases." (PMID 38495792, 2024). "ACTH, 17-OHP, and the aldosterone/renin ratio were all elevated in all 10 patients without treatment; 5 patients had hypokalemia, and 2 patients had hypernatremia." (PMID 37486441, 2024). "On the other hand, 3 patients had hypokalemia (mean renin 19.4 ± 2.8 mIU/L), but none had hypernatremia." (PMID 39416427, 2024). "PsA is characterized by hypokalemia, MA, and reduced renin level without an increase in aldosterone level." (PMID 37764649, 2023). "Concentrations of potassium and renin did not correlate in patients with a tendency for hypokalemia (r = -0.181, p=0.536)." (PMID 35813662, 2022). "Although it has been shown that the systemic renin–angiotensin system (RAS) is suppressed with age, activation of tissue RAS may play an important role in the pathogenesis of hypokalemia in older patients." (PMID 33830482, 2021). "Plasma biochemical results showed that one of proband’s sister (II-4) showed Gitelman syndrome-phenotypes with hypokalemia, hypomagnesaemia, elevated renin-aldosterone level, and normal blood pressure, but with normocalcemia and hypocalciuria." (PMID 32758178, 2020). "There was evidence of hypokalemia (data not shown) and plasma renin was suppressed even despite a 0.03% Na diet." (PMID 26077568, 2015). "Starting diuretic treatment in stage B2 cannot prevent or delay the occurrence of CHF, but it might lead to dehydration, hypokalemia, diuretic resistance, activation of the renin-angiotensin-aldosterone system, and last but not least to incontinent pets." (PMID 38473157, 2024). "For individuals exhibiting a low-renin phenotype, a PACCLEIA exceeding 10 ng/dL (or equivalently, a PACRIA greater than 20 ng/dL) or the presence of hypokalemia (serum potassium less than 3.5 mEq/L) may be sufficient to diagnose PA without the need for further confirmatory testing." (PMID 39877848, 2024). "For example, concentrations of renin were not systematically measured during the hypokalemic periods which could have added important information on the etiologies of hypokalemia." (PMID 35813662, 2022). "The use of ARR is well established as the most reliable screening method for PA, and in case settings, such as the one described (spontaneous hypokalemia with suppressed plasma renin levels and elevated aldosterone), there is no need for further confirmatory testing." (PMID 31565059, 2019). "If a young patient (<35 years) has marked aldosterone excess and spontaneous hypokalemia along with plasma renin levels below detection levels there may be no need for further confirmation testing." (PMID 27682153, 2016). "Some participants with hypokalemia might have other conditions that can lower potassium levels, such as primary aldosteronism, although we do not have information on plasma levels of aldosterone and renin." (PMID 40124766, 2025).
Hypokalemia (continued). "However, in the case of patients under the age of 35 with a detected unilateral adenoma of more than 10 mm and a structurally unaltered opposite adrenal gland, adrenal venous sampling is not mandatory if the aldosterone-to-renin ratio is higher than 30 ng/dl (831 pmol/l) and hypokalemia is evident." (PMID 31666819, 2019). "Imaging revealed an adrenal adenoma; however, low renin and aldosterone levels suggested that abiraterone-induced MES, rather than primary aldosteronism, was responsible for his hypokalemia." (PMID 40521126, 2025). "According to the Endocrine Society Guidelines 2016, in the setting of very low plasma renin levels, a plasma aldosterone concentration (PAC) of >20 ng/dL with spontaneous hypokalemia, one does not need to proceed with further confirmatory testing." (PMID 38978003, 2024). "Patients with FH1 have low renin, increased PAC, hypokalemia (in particular after the use of nonpotassium-sparing diuretics), and the presence of hybrid steroids 18-hydroxycortisol (18OHF) and 18-oxocortisol (18-oxoF); imaging studies are compatible with BAH." (PMID 35929903, 2022). "The patient presented with malignant hypertension, hypokalemia, and an aldosterone‐to‐renin ratio (ARR) of 0.53 indicative of secondary hyperaldosteronism, a condition of excessive renin secretion unresponsive to normal negative feedback mechanisms." (PMID 26997629, 2016). "The absence of hypokalemia in ACTZ/ACTZ-treated animals, despite severe volume depletion, increased renin/aldosterone pathway and metabolic alkalosis is intriguing." (PMID 24260196, 2013).
diabetic nephropathy (197 papers, 2008 to 2026). "ns-MRAs, prescribed for diabetic kidney disease, exhibit a high risk of hyperkalemia, particularly when combined with renin–angiotensin system inhibitors." (PMID 39937358, 2025). "Li’s review further underscored that diabetic nephropathy is a leading cause of kidney failure in diabetic patients, emphasizing the pivotal role of the renin–angiotensin–aldosterone system (RAAS) in the progression of kidney damage." (PMID 41561332, 2025). "The pathogenesis and development of diabetic nephropathy have been extensively linked to the renin‐angiotensin‐aldosterone system (RAS)." (PMID 37723622, 2023). "Initially, activation of the renin-angiotensin system causes glomerular hyperfiltration, a finding characterizes diabetic kidney disease (DKD) and CKD." (PMID 35459096, 2022). "Another possible explanation for the positive effect of LPD in diabetic nephropathy is linked to the renin-angiotensinsystem (RAS)." (PMID 29914534, 2018). "Renal renin-angiotensin system (RAS) activation is one of the important pathogenic mechanisms in the development of diabetic nephropathy in type 2 diabetes." (PMID 27802313, 2016). "Both kallikrein-kinin system (KKS) and renin-angiotensin system (RAS) have been implicated in the pathogenesis of diabetic nephropathy (DN)." (PMID 25918729, 2015). "Activation of the renin-angiotensin system (RAS) is thought to be the major mechanism underlying diabetic nephropathy." (PMID 24284398, 2013). "The imbalance of renin-angiotensin aldosterone system (RAAS) in diabetic nephropathy was also associated with changes in extracellular fluid volume." (PMID 24349311, 2013). "Regardless of the involved mechanism, the final common pathway of diabetic nephropathy is kidney fibrosis that is caused by kidney hemodynamic and ischemic abnormalities, oxidative stress and the overactivation of the renin-angiotensin aldosterone system (RAAS)." (PMID 35484505, 2022). "Consequently, genes involved in the renin-angiotensin system have been suggested as potential genetic predispositions for the development of diabetic nephropathy." (PMID 25587546, 2014). "Diabetic nephropathy is associated with the renin–angiotensin–aldosterone system and lead to salt and water retention, causing left ventricular hypertrophy, and subsequent diastolic dysfunction with volume overload of the atria, which in turn may lead to AF by atrial dilatation." (PMID 34426643, 2021). "The activation of the renin-angiotensin system, such as angiotensin II, which is common in diabetic kidney disease and hypertensive nephropathy, is involved in renal damage progression, and associated with reduced pyruvate kinase M2 function." (PMID 40980659, 2025). "Although RAAS antagonists are a cornerstone in the treatment of diabetic nephropathy, their effectiveness is often hampered by a compensatory increase in renin levels." (PMID 41561332, 2025). "The development of diabetic kidney disease (DKD) involves the upregulation of the renin–angiotensin–aldosterone system (RAS) and alterations in renal hemodynamics with glomerular hypertension, ischemia, and oxidative stress." (PMID 40660221, 2025). "The renin-angiotensin system (RAS) is one further explanation for the beneficial effects of LPD in diabetic nephropathy as it is considered to be involved in most of the pathological processes that result in diabetic nephropathy." (PMID 39897826, 2025). "Despite decades of clinical efforts targeting glycemic control and renin-angiotensin system blockade, diabetic kidney disease (DKD) remains responsible for nearly half of global ESKD cases, underscoring critical gaps in current therapeutic strategies." (PMID 40640102, 2025). "In diabetic nephropathy, oxidative stress activates the renin-angiotensin-aldosterone system (RAAS) that damages the kidney." (PMID 40699692, 2025).